CXCR5 (C-X-C motif chemokine receptor 5)
Diseases named in the same sentence as CXCR5 in open-access papers (continued):
Sharing a sentence is not in itself a finding about the gene and the disease.
Hyperglycemia (1 paper, 2020). An increased concentration of glucose in the blood. "In this study, CXCL13, a typical chemokine for recognizing and recruiting CXCR5+ cells 15, was elevated in retina at the setting of hyperglycemia, probably facilitating migration of Tfh cells into diabetic retinae." (PMID 32226551, 2020).
hypersensitivity pneumonitis (1 paper, 2022). Hypersensitivity pneumonitis (HP) is a pulmonary disease with symptoms of dyspnea and cough resulting from the inhalation of an antigen to which the subject has been previously sensitized. "The strong evidence for the crucial involvement of the CXCR5 : CXCL13 axis in lymphoid cell biology and in facilitating cell-cell interactions that promote lymphocyte infiltration fuels speculation of potentially successful immune-targeted therapies in patients with hypersensitivity pneumonitis." (PMID 36164329, 2022).
idiopathic pulmonary fibrosis (1 paper, 2019). Idiopathic pulmonary fibrosis (IPF) is a nonneoplastic pulmonary disease that is characterized by the formation of scar tissue within the lungs in the absence of any known cause. "Recently, CXCL13, a ligand of CXCR5, has been reported to increase in the peripheral blood and lungs of patients with idiopathic pulmonary fibrosis (IPF)." (PMID 31694639, 2019).
IgG4-related disease (1 paper, 2024). "In IgG4-related disease and Kimura disease, prominent IgG4 class switching is thought to be controlled by a population of Tfh cells co-expressing CXCR5, PD-1, ICOSL, IL-10, IL-4 and LAG-366,67." (PMID 39013889, 2024).
Impaired glucose tolerance (1 paper, 2022). An abnormal resistance to glucose, i.e., a reduction in the ability to maintain glucose levels in the blood stream within normal limits following oral or intravenous administration of glucose. "Children with impaired glucose tolerance and T1D exhibit a higher frequency of CXCR5+PD-1+ICOS+, CD4+CXCR5+, and CD4+CXCR5+ICOS+ circulating follicular helper T cells (Tfh)." (PMID 36704045, 2022).
Infertility (1 paper, 2012). "Although we did not note occluding fibrosis which is associated with infertility, oviduct dilation was also noted in Cxcr5−/− (arrowhead)." (PMID 23189125, 2012).
inflammatory demyelinating neuropathy (1 paper, 2019). "Considering the potential role of SCs as APCs24, these findings suggest that the CXCL13/CXCR5-mediated local immune reaction involving SCs may contribute to the development of autoimmune reaction in inflammatory demyelinating neuropathy." (PMID 31712675, 2019).
interstitial cystitis (1 paper, 2025). A rare chronic debilitating urogenital disease characterized by urinary frequency, urgency, and pelvic pain. "CXCL13, a B cell chemokine, and its receptor CXCR5 form a chemotactic axis whose aberrant activation drives B cell-mediated immune responses, thereby promoting inflammatory processes and endothelial injury, which are implicated in the pathophysiology of interstitial cystitis/bladder pain syndrome." (PMID 41196851, 2025).
ischemia reperfusion injury (1 paper, 2019). Adverse functional, metabolic, or structural changes in ischemic tissues resulting from the restoration of blood flow to the tissue (reperfusion), including swelling; hemorrhage; necrosis; and damage from free radicals. "Our findings suggest that the chemokine receptor CXCR5 may protect retina from ischemia-reperfusion injury by its anti-inflammatory effects." (PMID 31355256, 2019).
joint disease (1 paper, 2016). "The finding that CXCR5+Th17 cell frequency at baseline correlates with swollen joints at baseline and at one year post-TNFi therapy could indicate that patients with high CXCR5+Th17 frequencies have more severe joint disease, which is therefore more refractory to therapy." (PMID 28004828, 2016).
latent infection (1 paper, 2026). "Since latent infection persists lifelong in B cells, the presence of stem-like CXCR5+ CD8+ T cells in close proximity to these reservoirs may be a key mechanism preventing viral reactivation and transformation." (PMID 41499499, 2026). "On the basis of these findings, it seems reasonable to propose that CXCR5+ memory CD8+ T cells are optimally configured and positioned to maintain localized immunity against latent infections with a predilection for LTs, epitomized here by EBV." (PMID 41499499, 2026).
latent syphilis (1 paper, 2023). A stage of syphilis characterized by the serologic evidence of infection by Treponema pallidum without evidence of accompanying signs or symptoms related to the disease. "Peripheral blood samples from 30 HCs, 24 secondary syphilis infection patients and 41 latent syphilis patients were analyzed by flow cytometry, and CD4+CXCR5+CD25lowCD127intermediate-highTfh cells were identified." (PMID 37901207, 2023).
leishmaniasis (1 paper, 2023). Infectious disease that is transmitted through the bite of hematophagous female phlebotomine sand flies. "Our findings raise the possibility that CXCR5+ cells could exert some control over leishmaniasis, as we observed that these cells retain their ability to proliferate and produce IFN-γ in response to polyclonal stimulation." (PMID 37691941, 2023).
liver cirrhosis (1 paper, 2015). "The frequency of circulating CXCR5+CD4+ T cells was significantly decreased in HCC patients compared with HBV-relative liver cirrhosis (LC) patients and healthy controls, and the decrease in circulating CXCR5+CD4+ T cells correlated with disease progression." (PMID 25689070, 2015).
lung disease (1 paper, 2024). "Furthermore, a significant positive correlation was observed between CD4+ CXCR5+ lymphocyte levels and the severity of lung disease according to the Medsger disease severity index." (PMID 38280030, 2024). "A positive correlation was found between the severity of lung disease and CD4+ CXCR5+ T lymphocyte levels in patients with SSc (p = 0.01, r = 0.358)." (PMID 38280030, 2024).
Lymphadenopathy (1 paper, 2025). Enlargement (swelling) of a lymph node. "Marked CXCR5 down‐regulation occurs in active TU and could explain the unique absence of lymphadenopathy." (PMID 40469525, 2025).
measles (1 paper, 2018). A highly contagious viral infection caused by the measles virus. "We observed a significant increase in the frequency of circulating CXCR5+ Tfh cells after measles." (PMID 30470742, 2018).
meningoencephalitis (1 paper, 2021). Inflammation of the meninges and brain, generally secondary to an infectious cause. "This sub-analysis accordingly underlined a broader function of CXCL13/CXCR5 signaling in meningoencephalitis and corroborated earlier observations linking persistent CXCL13 elevations with severe disease courses in bacterial and viral CNS infections." (PMID 34446066, 2021). "Summing up, we found a clear link between intrathecal CXCL13 elevations and CXCR5+CD4 T cells in particular in meningoencephalitis patients and CXCR5+CD4 T cell correlating with B cell frequencies in neuroimmunological disorders." (PMID 34446066, 2021).
metastasis (1 paper, 2022). The spread or migration of cancer cells from one part of the body (where they first appeared) to another. "In addition, it was also discovered that the CD4+CXCR5+Tfh cell ratio in the metastasis group also increased significantly." (PMID 35494526, 2022).
metastatic tumors (1 paper, 2021). "As shown, there are more CXCR5+CD8+T cells in lower pathological T stage and non-metastatic tumors." (PMID 34035252, 2021).
minimal change disease (1 paper, 2014). "This study is aimed at examining the frequencies of different subsets of CD4+CXCR5+ TFH cells in adult patients with minimal change disease (MCD)." (PMID 25243187, 2014).
myocardial infarction (1 paper, 2020). Gross necrosis of the myocardium, as a result of interruption of the blood supply to the area, as in coronary thrombosis. "After further analysis of the expression quantitative feature loci of the gene expression data set, the G allele of rs77564610 and high expression of CXCR5 in the whole blood were found to be closely related to the high risk of myocardial infarction." (PMID 33052139, 2020).
nematode infection (1 paper, 2025). "Collectively, these data strongly suggest that Chi3l1 expression by both CD4 T cells and the CXCR5+ cDC2 cells promotes TH2 development following nematode infection." (PMID 41012147, 2025).
neurosyphilis (1 paper, 2022). Infection of the brain or spinal cord by Treponema pallidum. "CXCL13/CXCR5 mediated the aggregation of B cells, which directed the aberrant humoral immune responses via the formation of EGCs, suggesting neurological damage in neurosyphilis." (PMID 36419997, 2022).
non-alcoholic fatty liver disease (1 paper, 2025). "CHRNA7 has been implicated in the regulation of inflammation in non-alcoholic fatty liver disease, while CXCR5 is known to play a role in cancer-related inflammation and immune responses." (PMID 40705171, 2025).
ocular hypertension (1 paper, 2019). Abnormally high intraocular pressure. "In conclusion, our findings demonstrated that the chemokine receptor CXCR5 may prevent neuroinflammation via inhibiting the activation of microglia cells and maintaining the integrity of the iBRB barrier in retinal I/R model induced by acute ocular hypertension." (PMID 31355256, 2019).
ocular toxoplasmosis (1 paper, 2022). Ocular toxoplasmosis is an infection in the eye caused by the parasite, Toxoplasm a gondii. "It has been shown that the expression levels of CXCR5 were very low during murine ocular toxoplasmosis." (PMID 35177094, 2022).
oral squamous cell carcinoma (1 paper, 2019). "c-Myc activation through the CXCL13:CXCR5 signaling axis stimulates RANKL expression in stromal/preosteoblast cells, therefore implicating CXCL13 as a potential therapeutic target to prevent oral squamous cell carcinoma invasion of bone/osteolysis." (PMID 31354634, 2019).
periodontal disease (1 paper, 2019). "It has been reported that during periodontal disease the expression of CD4+, CXCR5+, and CCR5+ is increased; the latter has also been reported increased in smokers." (PMID 31316513, 2019).
peritonitis (1 paper, 2012). Inflammation of the peritoneum (tissue that lines the abdominal wall and covers most of the organs in the abdomen). "We observed a similar reduction in B1-a B cell frequency in PECs, yet the disappearance was more gradual and was preceded by a dramatic reduction in total B cell CXCR5 expression These differences are not entirely surprising, as LPS-induced peritonitis is distinct from that induced by MHV68." (PMID 22952645, 2012).
Pneumocystis infection (1 paper, 2022). "In addition, CXCR5-/- mice lacked draining LNs and presented poorly organized iBALT structures in the lung after Pneumocystis infection." (PMID 35309354, 2022).
polyp (1 paper, 2016). A usually exophytic mass attached to the underlying tissue by a broad base or a thin stalk. "IL-21-expressing CD8+ T cells in polyp tissues expressed higher CXCR5, PD-1, and ICOS levels than cells in control tissues and showed significantly higher T-bet and Bcl-6 expression levels compared with IL-21−CD8+ T cells." (PMID 27468819, 2016). "Some of the IL-21-producing CD8+ T cells in polyp tissues co-expressed IFN-γ, CXCR5, PD-1, ICOS, T-bet and Bcl-6, which display the T follicular helper (Tfh) cell functionality." (PMID 27468819, 2016). "Moreover, the percentage of CXCR5+IL-21+, ICOS+IL-21+ and PD-1+IL-21+ cells in CD8+ T cells was higher in polyp tissues than in control sinonasal tissues (P < 0.01)." (PMID 27468819, 2016). "The expression of CXCR5, PD-1 and ICOS on CD8+ T cells in polyp tissues was significantly increased compared with control tissues (P < 0.01), and some IL-21-expressing CD8+ T cells were found to co-express CXCR5, ICOS and PD-1 in polyp tissues." (PMID 27468819, 2016).
preeclampsia (1 paper, 2023). Preeclampsia is a hypertensive disorder of pregnancy that is characterized by new-onset hypertension with proteinuria presenting after 20 weeks of gestation, and depending on mild or severe forms may initially present with severe headache, visual disturbances, and hyperreflexia. "The authors of the publication emphasized the role of OX40 and CXCR5 overexpression in the production of autoantibodies by B lymphocytes, which is one of the components of the pathogenesis of preeclampsia." (PMID 37887878, 2023).
prion disease (1 paper, 2017). A transmissible disease that is caused by a protein that is able to induce abnormal folding of normal cellular proteins, leading to characteristic spongiform brain changes, which are associated with neuronal loss without an inflammatory response. "Since oral exposure to a limiting dose of ME7 scrapie prions typically yields a disease incidence of <100% in wild-type (control) mice, it was used here to enable the effects of conventional DC-restricted CXCR5-deficiency on survival time and prion disease susceptibility to be determined." (PMID 28275192, 2017). "Oral prion disease susceptibility is reduced in the specific absence of CXCR5-expressing conventional DC." (PMID 28275192, 2017). "Conventional DC-specific CXCR5 deficiency does not influence prion disease susceptibility when infection is established directly within the CNS." (PMID 28275192, 2017). "Therefore, a CXCR5 deficiency specifically in conventional DC did not affect prion disease pathogenesis or susceptibility when the infection was established directly within the CNS." (PMID 28275192, 2017). "The distribution and severity of the spongiform pathology was also similar in the brains of all the clinically affected mice, indicating that conventional DC-specific CXCR5 deficiency did not alter the course of CNS prion disease once neuroinvasion had occurred." (PMID 28275192, 2017).
pulmonary arterial hypertension (1 paper, 2025). Pulmonary arterial hypertension (PAH) is a group of diseases characterized by mean pulmonary artery pressure >20 mmHg and elevated pulmonary arterial resistance leading to right heart failure. "In contrast, endothelial cells largely express several other chemokine receptors including CCR4, CCR5, CCR6, CXCR2, CXCR4, and CXCR5, and CXCR4, which plays a key role in pulmonary arterial hypertension (PAH) through an autocrine signaling mechanism." (PMID 40859641, 2025).
rash (1 paper, 2023). "In patients with a skin rash, the proliferative activity of CD8Tem, dnCD3T, and CXCR5− DNB were significantly elevated (rash+: 2.031%, rash‐: 0.512%, P = 0.00066; rash+: 0.710%, rash‐: 0.315%, P = 0.00035, and rash+: 0.167%, rash‐: 0.059%, P = 0.00083, respectively)." (PMID 35997780, 2023). "In patients with renal involvement, the proliferative activity of cMo, APC, and CXCR5− DNB was significantly elevated (rash+: 0.869%, rash‐: 0.280%, P = 0.00136; rash+: 0.282%, rash‐: 0.168%, P = 0.00112; and rash+: 0.138%, rash‐: 0.060%, P = 0.00083, respectively)." (PMID 35997780, 2023).
renal carcinoma (1 paper, 2021). A carcinoma arising from the epithelium of the renal parenchyma or the renal pelvis. "CXCR5 was found to be a poor predictive factor for renal cancer in a prognostic study." (PMID 34922542, 2021).
retinal diseases (1 paper, 2019). "Although more and more researches have been conducted on the chemokine receptor CXCR5, little attention has been paid to its role in retinal diseases such as ischemia-reperfusion (I/R) injury." (PMID 31355256, 2019).
scrapie (1 paper, 2017). A fatal disease of the nervous system in sheep and goats, characterized by pruritus, debility, and locomotor incoordination. "In order to determine the effects of conventional DC-specific CXCR5-deficiency on oral prion pathogenesis, groups of CXCR5ΔDC mice and CXCR5F/F mice were orally exposed to ME7 scrapie prions and Peyer's patches, MLN, and spleens collected at intervals afterwards (n = 4/group)." (PMID 28275192, 2017).
seminoma (1 paper, 2024). A radiosensitive malignant germ cell tumor found in the testis (especially undescended), and extragonadal sites (anterior mediastinum and pineal gland). "CXCR5 + BCL6+ Tfh cells were identified in all TGCT locations with the highest percentage (0.05–2.40%, median of 0.30%) in the seminoma “Tumor”." (PMID 38649788, 2024). "Importantly, a high density of cells expressing Treg-specific markers CD25 and FOXP3, or Tfh-specific markers CXCR5 and BCL6, were found mainly in seminoma." (PMID 38649788, 2024).
sickle cell disease (1 paper, 2022). Sickle cell anemias are chronic hemolytic diseases that may induce three types of acute accidents: severe anemia, severe bacterial infections, and ischemic vasoocclusive accidents (VOA) caused by sickle-shaped red blood cells obstructing small blood vessels and capillaries. "In addition, in polytransfused sickle cell disease patients, high levels of CXCR5+PD1+CD4+ T lymphocyte (TL) may be a biomarker for the inhibited functions of T cells." (PMID 35479938, 2022).
spondyloarthritis (1 paper, 2025). "The significant differences in CXCR5 circulating methylation observed between RA and SLE relative to spondyloarthritis could impact CXCR5 and its associated immune processes, leading to different disease manifestations." (PMID 39835879, 2025).
synovitis (1 paper, 2025). Inflammation of a synovial membrane. "CXCL13 is involved in recruiting CXCR5+ B cells to synovium in RA and was associated with disease activity, ultrasonographic synovitis and long-term radiographic progression." (PMID 39925810, 2025).
temporal lobe epilepsy (1 paper, 2021). A localization-related (focal) form of epilepsy characterized by recurrent seizures that arise from foci within the temporal lobe, most commonly from its mesial aspect. "CXCR5, the only known receptor for the chemokine CXCL13, is known to mediate neuroinflammation and thereby contribute to impairment of learning and memory in intractable temporal lobe epilepsy patients and pilocarpine-induced epileptic rats." (PMID 34711216, 2021).
trigeminal neuralgia (1 paper, 2016). Trigeminal neuralgia is a nerve disorder that causes a stabbing or electric-shock-like pain in parts of the face. "Thus, targeting the CXCL13/CXCR5/ERK/TNF-α and IL-1β pathway in the TG may provide a novel therapeutic approach for the treatment of the trigeminal neuralgia." (PMID 27401148, 2016).
triple-negative breast carcinoma (1 paper, 2024). An invasive breast carcinoma which is negative for expression of estrogen receptor (ER), progesterone receptor (PR), and human epidermal growth factor receptor 2 (HER2). "High expression of CXCR4 or CCR5 on tumor was found to be associated with poor prognosis, and CXCR5 on tumor was associated with poor chemotherapy response in the present cohort with locally advanced triple-negative breast cancer." (PMID 39001456, 2024). "To our knowledge, we report in this study for the first time that CXCR5 expression on TILs was found to be correlated with better chemotherapy response and a good outcome in triple-negative breast cancer." (PMID 39001456, 2024).
type 1 diabetes (1 paper, 2019). "Our initial analyses indicate that TIGIT, an immunomodulatory receptor also expressed at high levels by CXCR5+PD1hi Tfh cells in blood and tonsils, shows promise as a candidate auxiliary marker for the identification of potentially pathogenic Tph cells in individuals with type 1 diabetes." (PMID 31270583, 2019). "In conclusion, we demonstrate that both CXCR5−PD-1hi Tph and CXCR5+PD-1hi Tfh cells are increased in the blood of children with newly diagnosed type 1 diabetes, especially in children with multiple autoantibodies." (PMID 31270583, 2019). "In line with our published results, the frequency of CXCR5+PD-1hi Tfh cells was, however, only increased in children with type 1 diabetes." (PMID 31270583, 2019). "To analyse whether changes in circulating CXCR5−PD-1hi Tph cell frequencies are altered in human type 1 diabetes, we re-analysed data from our large published study evaluating the frequencies of CXCR5+ Tfh cells at different stages of type 1 diabetes progression." (PMID 31270583, 2019).